CXCL12 (C-X-C motif chemokine ligand 12)
Diseases named in the same sentence as CXCL12 in open-access papers (continued):
Sharing a sentence is not in itself a finding about the gene and the disease.
prostate carcinoma (continued). "Infiltrating ASCs from perioprostatic WAT have also been shown to play a role in obesity driven systemic therapy resistance and prostate cancer progression via production of CXCL12 and other chemokines." (PMID 39840030, 2024). "Our group has shown that obesity is associated with both TAM function and infiltration of adipose stromal cells (ASCs) producing CXCL12 and other chemokines that lead to increased progression of prostate cancer." (PMID 39840030, 2024). "CXCL12 (SDF-1)/CXCR4 interactions play an essential role in prostate cancer migration and invasion to the bone by activating Akt1 and MMP-9 expressions." (PMID 36863017, 2023). "The CXCL12/CXCR4 axis has previously been shown to be involved in prostate cancer cell homing to bone tissue, and new investigations found a novel interaction of Phosphatidyl Inositol 4 kinase IIIa (PI4KA) downstream of chemokine signaling." (PMID 38239314, 2023). "CXCL12/CXCR4 signaling in prostate cancer cells has been shown to express several members of soluble and membrane-type metalloproteinases, MMP-1, MMP-2, MMP-3, MMP-9, MMP-10, MMP-11, and MMP-14 whose expression contribute to cellular migration and invasion." (PMID 38239314, 2023). "Overexpression of PGK1 in prostate cancer cells has been reported to increase cell metastasis through the CXCR4/CXCL12 axis." (PMID 36860848, 2023). "SILAC-based quantitative proteomic analysis of lipid raft microdomains identified phosphatidylinositol 4-kinase III-alpha (PI4KA) as a novel downstream modulator of CXCL12/CXCR4 signaling in prostate cancer cells." (PMID 38239314, 2023). "Studies to understand the cause of Treg cells migration into bone compartment in prostate cancer patients revealed that chemokine CXCL12, known for its role in stimulating tumor growth, was higher in prostate cancer patients with bone metastasis." (PMID 36836690, 2023). "Osteoblasts in bone marrow express CXCL12, promoting prostate cancer cell invasion of the niche by chemokine signaling by CXCR4 on the invading cells." (PMID 38239314, 2023). "In prostate cancer, CAFs can recruit and activate monocytes to generate M2 macrophages via CXCL12 and CXCL14." (PMID 36418470, 2023). "CXCL12 secreted by stroma cells plays a pivotal role in bone metastasis, and blocking the CXCL12/CXCR4 axis significantly inhibited the BoM process in prostate cancer." (PMID 38187400, 2023). "For example, overexpression of RGS1 inhibited CXCL12-mediated human plasmacytoma cell migration, and epigenetic inhibition of RGS2 has been associated with prostate cancer progression and overexpression of RGS5 on lung cancer cells." (PMID 35646090, 2022). "Drug-induced tubulin acetylation and MT stabilization are suppressed upon CXCL12 activation in prostate cancer cells." (PMID 36129937, 2022). "Prostate cancer cells expressing the secreted glycoprotein Olfactomedin 4 (OLFM4) show a reduced bone metastasis due to an inhibited CXCL12-mediated AKT phosphorylation." (PMID 34064589, 2021). "For example, prostate cancer derived-exosomal PKM2 from the bone marrow promoted premetastatic niche formation through the up-regulation of CXCL12 in bone marrow stromal cells." (PMID 33456577, 2021). "Bone marrow mesenchymal stem cell-secreted CXCL12 induces migration of prostate cancer cells via activation of AKT." (PMID 34064589, 2021). "Slug was also found to enhance migration and invasion of prostate cancer cells by activating the CXCR4/CXCL12 axis." (PMID 34118928, 2021). "The CXCR4/CXCL12 axis plays essential roles in all stages of prostate cancer progression, including bone metastasis." (PMID 33535458, 2021). "Consistently, stimulation of prostate cancer stem cells with CXCL12 was shown to induce AKT-mediated bone metastasis." (PMID 34064589, 2021). "Previous studies have shown that the CXCL12/CXCR4 chemokine axis plays a critical role in localizing tumor cells to the bone marrow during the early stages of bone metastasis in prostate cancer." (PMID 35177982, 2021).
prostate carcinoma (continued). "CXCL12 was reported to be upregulated by cabozantinib to promote infiltration of neutrophils into the tumor bed in murine prostate cancer." (PMID 33954115, 2021). "In this study, UA was found to downregulate CXCR4 in prostate cancer cells, which correlated with an inhibition of CXCL12-induced migration, reducing metastasis of prostate cancer cells." (PMID 34439409, 2021). "Cabozantinib triggers the release of CXCL12, resulting in robust neutrophil infiltration into the tumor bed and near-complete clearance of poorly differentiated murine prostate cancer." (PMID 34834449, 2021). "Recent research has shown that the CXCL12 expression level in prostate cancer was obviously higher than that in benign prostatic hyperplasia tissue." (PMID 34659412, 2021). "For instance, the chemokine receptor CXCR4 on breast or prostate cancer cells mediates the chemoattractive effect of osteoblast-derived C-X-C motif chemokine 12 (CXCL12) for the homing of tumor cells to the bone marrow." (PMID 34064589, 2021). "Prostate cancer cell lines that overexpress CXCR4 tend to migrate to organs with high levels of C-X-C motif chemokine ligand 12 (CXCL12), such as the bone marrow." (PMID 33804975, 2021). "The specific blockade of the CXCL12/CXCR4 axis in prostate cancer cells using hTERT promoter induced knockdown of CXCR4 decreased bone metastasis." (PMID 32585812, 2020). "In prostate cancer, CXCR4 is overexpressed, and a loss of the tumour suppressor PTEN was reported to activate Akt and regulate the CXCL12/CXCR4 signalling pathway in metastasis." (PMID 32731484, 2020). "For example, suppression or down-regulation of DPP4 promotes prostate cancer progression via reduced degradation of its substrate CXCL12, leading to enhanced signalling via CXCR4 and increased invasion and metastatic spread to peripheral organs in vivo." (PMID 33143089, 2020). "In another instance, migration and invasion was shown to be decreased following suppression of the CXCL12/CXCR7 axis in cell lines derived from an obesity-driven mouse model of Hi-Myc prostate cancer." (PMID 32585812, 2020). "Prostate cancer cells at primary sites released exosomes containing pyruvate kinase M2, which enhanced CXCL12 production by bone marrow stromal cells in a hypoxic inducible factor (HIF)-1α-dependent manner, giving rise to pre-metastatic niche." (PMID 33050237, 2020). "Blocking the CXCL12/CXCR4 axis via usage of a CXCR4 receptor antagonist (AMD3100) or antibody in prostate cancer cells, however, decreased tumor size and the population of progenitor cells." (PMID 32585812, 2020). "In several prostate cancer cell lines, acetyl-l-carnitine acted as an anti-prostate cancer agent by inhibiting the production of chemokines CXCL12 and CCL2 as well as CXCR4 (chemokine ligand-receptor) and pro-inflammatory cytokines (IFN-γ and TNF-α)." (PMID 32370025, 2020). "The resultant effect of this action is the consequential release of CXCL12 by the CAFs to facilitate metastasis via induction of EMT in the prostate cancer cells." (PMID 32585812, 2020). "CXCL12 is a homeostatic chemokine secreted by stromal cells in the bone marrow (including osteoblast) and high expression of CXCL12 is observed in metastatic tissues of prostate cancer." (PMID 32585812, 2020). "Apart from all these, the involvement of the CXCL12/CXCR7 axis in metastasis of prostate cancer has also been documented in literature." (PMID 32585812, 2020).
prostate carcinoma (continued). "Human prostate carcinoma-associated fibroblasts and prostate cancer cells orchestrate and enhance TAM and MDSC recruitment to prostate tumors as well as M2-like TAM differentiation by the chemokines CCL2, CXCL12, and IL-6 during cancer progression." (PMID 32824865, 2020). "Another important cytokine that promotes CTCs homing is CXCL12, and the enhanced activation of the CXCL12/CXCR4 axis has been linked with prostate cancer metastasis." (PMID 32585812, 2020). "Although the complete CXCL12/CXCR4-mediated molecular mechanisms through which prostate cancer cells re-establish themselves to the bone are still subject to further investigations, several probable mechanisms have, however, been proposed." (PMID 32585812, 2020). "CXCL12 and its receptor CXCR4 are known as key regulators of highly migratory/invasive phenotype of prostate cancer and their expression is associated with metastatic disease and poor survival." (PMID 31718684, 2019). "CXCL12 treatment of prostate cancer cells results in increased αvβ3 expression and receptor affinity, which enhances cell adhesion to human bone marrow cells and their ability to bind to the ECM protein vitronectin." (PMID 29642534, 2018). "CXCR7 is an alternative receptor for CXCL12, and is also increased in prostate cancer tissues displaying correlations with tumor stage and bone metastases." (PMID 29642534, 2018). "In a series of experiments by the Taichman group, osteoblast-derived CXCL12 (SDF-1) was found to mediate bone metastatic prostate cancer progression via binding of its receptor CXCR4 on the prostate cancer cells." (PMID 29867053, 2018). "The role of CXCL12 in homing to the bone is further supported by in vitro migration assays that demonstrated that the breast and prostate cancer cells migrate towards CXCL12 and osteoblasts, which is dependent on CXCR4." (PMID 29642534, 2018). "We found evidence that the drebrin/EB3 pathway is important in prostate cancer cell invasion and the chemotactic response to the chemokine CXCL12." (PMID 28319065, 2017). "In that study, two scFvs were selected against CXCR4 and their inhibitory effects on CXCL12- mediated prostate cancer cell activation was investigated." (PMID 28491282, 2017). "The CXCR4/CXCL12 axis plays a central role in systemic metastasis of prostate carcinoma (PCa), thereby representing a promising target for future therapies." (PMID 27462860, 2016). "CAFs have been shown to induce EMT and ultimately metastasis of murine prostate cancer cells by secreting CXCL12." (PMID 26954362, 2016). "In prostate cancer, CAFs have been shown to affect the proliferation and facilitate the invasiveness of cancer cells by CXCL12, CXCL14, MMP2 and MMP3." (PMID 26954362, 2016). "Wang and colleagues reported that pomegranate juice and its constituents were able to inhibit chemotaxis acting on CXCL12 in different hormone-dependent and -independent prostate cancer cells (DU145, PC3, and LNCaP)." (PMID 26180600, 2015). "Overall, these findings demonstrate that acute stimulation by chemokines CXCL11 and CXCL12 influences intracellular protein metabolism and/or protein trafficking in AD-LNCaP prostate-cancer cells." (PMID 25884570, 2015). "Overall, these results show that homeostatic levels of CXCR4 protein require CXCR7 expression, and that CXCR4 expression is required for CXCL12-mediated motility in LNCaP prostate-cancer cells." (PMID 25884570, 2015). "A similar up-regulation of CXCR4 in response to CXCL12, mediated through NF-κB, has been reported in prostate cancer cells." (PMID 25774696, 2015). "Basal mRNA expression for CCL2 and CXCL12 was lower in each of the prostate cancer cell lines relative to the expression detected in the WPMY-1 prostate stromal fibroblast or the monocytic THP-1 cell lines." (PMID 24970800, 2014).
prostate carcinoma (continued). "AR signaling was shown to activate CXCR4 protein expression through KLF5 in prostate cancer cells, propelling chemotactic migration in response to CXCL12, a chemokine abundantly present in the microenvironment and specific sites of metastasis." (PMID 24429391, 2014). "Combined inhibition of both CXCL8 and CXCL12 signaling was more effective in inhibiting fibroblast-promoted cell motility while repression of CXCL8 attenuated CCL2-promoted proliferation of prostate cancer cells." (PMID 24970800, 2014). "As opposed to cultured cancer cells, in vivo bone tumors express CXCL12 in prostate cancer cells in addition to osteoblasts and endothelial cells." (PMID 24472670, 2014). "We investigated the role of CXCL8, CCL2 and CXCL12 in regulating the growth and survival of prostate cancer cells, independently or in a co-dependent manner." (PMID 24970800, 2014). "In prostate cancer cells, CXCL12 and CXCR4 play a key role in invasion and metastasis, leading to development and expansion of osseous metastasis." (PMID 24472670, 2014). "CXCL12/CXCR4 signaling has been shown to modulate the expression of angiogenic cytokines/chemokines in prostate cancer cells." (PMID 24472670, 2014). "Overexpression and increased activity of three specific chemokines termed CCL2, CXCL12 and CXCL8 have been strongly implicated in the progression of prostate cancer." (PMID 24970800, 2014). "In summary, these data showed that PTEN loss-induced PI3K/Akt pathway induces CXCL12/CXCR4 expression, and this expression is particularly mediated by Akt kinase in both murine and human prostate cancer cells." (PMID 23902739, 2013). "At the same time, chemokine receptor CXCR4 and its ligand CXCL12 mediate the adherence of prostate cancer cells to ECs, facilitating tumor invasiveness and metastatic progression." (PMID 24386459, 2013). "Prostate cancer frequently metastasizes to the bone, and previous studies implicate key role for CXCL12/CXCR4 signaling in bone metastasis." (PMID 23902739, 2013). "Chronic inflammation is associated with CXCL12, CCL5, and CCL2, which are highly overexpressed in prostate cancer." (PMID 23362217, 2013). "The CXCL12-induced adhesion of prostate cancer cells to the extracellular matrix is mediated by integrins." (PMID 22359577, 2012). "The studies reported herein show that the CXCR4/CXCL12 axis, a key regulator of tumor dissemination, plays a role in the maintenance of prostate cancer stem-like cells." (PMID 22359577, 2012). "It is known that activation of the CXCR4/CXCL12 pathway alters the adherence, migration, and invasion of cancer cells, including prostate cancer." (PMID 22359577, 2012). "Our data suggest that CXCL12 regulates the adhesion of CD133+/CD44+ prostate cancer progenitors to the extracellular protein fibrionectin which is important for distal organ seeding and initiation of secondary tumors." (PMID 22359577, 2012). "Herein we report studies that suggest the CXCR4/CXCL12 axis is activated in prostate cancer progenitors and plays a role in self-renewal, differentiation potential, cell adhesion, and tumorigenicity." (PMID 22359577, 2012). "CXCL12 stimulates chemotaxis of metastatic prostate cancer cells expressing a high level of CXCR4 and accelerates their migration." (PMID 22074556, 2011). "Our current findings indicate that CXCL12 is expressed in prostate cancer cells and was induced by SLUG." (PMID 22074556, 2011). "We provide the first compelling evidence that upregulation of autocrine CXCL12 is a major mechanism underlying SLUG-mediated migration and invasion of prostate cancer cells." (PMID 22074556, 2011). "In this study, we examined the regulation of the Slug-CXC4R/CXCL12-metastasis triangle in an in vitro cell culture model of human prostate cancer cells." (PMID 22074556, 2011). "CXCL12/CXCR4 ligand receptor interaction is involved in the directional migration of metastatic prostate cancer cells." (PMID 22074556, 2011).
prostate carcinoma (continued). "We used gain- and loss-of-function approaches to demonstrate that SLUG is a positive regulator of CXCL12 in prostate cancer cells." (PMID 22074556, 2011). "Our findings add support that CXCL12 are a potential therapeutic target for prostate cancer metastasis." (PMID 22074556, 2011). "We found that SLUG positively regulates expression of the CXCL12/CXCR4 axis in human prostate cancer cell lines." (PMID 22074556, 2011). "Our findings suggest that prostate cancer cells can gain invasive characteristics through upregulation of autocrine CXCL12." (PMID 22074556, 2011). "Conversely, blockade of CXCR4/CXCL12 interaction in prostate cancer cells via CXCR4 knockdown significantly inhibits bone metastasis in vivo." (PMID 22074556, 2011). "Together, our findings indicate that Slug positively regulates MMP9 expression, possibly via CXCR4/CXCL12 pathway in prostate cancer cells." (PMID 22074556, 2011). "Treatment of prostate cancer cells with CXCL12 increase their adhesion to a bone-marrow derived endothelial cell monolayer in culture." (PMID 21603150, 2011). "Because our data show that SLUG positively regulated both CXCL12 and CXCR4; therefore, we assessed the role of CXCL12 in SLUG-mediated prostate cancer invasion." (PMID 22074556, 2011). "Overall, our data indicate that CXCL12 is a key mediator for SLUG-induced migration and invasion of human prostate cancer cell lines in vitro; thereby suggesting that autocrine CXCL12 is an important factor for tumor metastasis." (PMID 22074556, 2011). "It plays a critical role in metastatic processes as shown for breast, ovarian and prostate cancer and CXCL12 is highly expressed in organs which are frequent sites of distant metastases like lung, liver and lymph nodes." (PMID 20386750, 2010). "Taichman showed that PC3 and DU145 prostate cancer cell lines and hormone-resistant LnCaP and C4-2B prostate cancer cell lines can express CXCL12." (PMID 18983683, 2008). "Human osteoblastsexpress CXCL12 mRNA and protein, whereas prostate cancer cells express CXCR4mRNA and receptor." (PMID 18779872, 2008). "CXCL12 expression in prostate cancer was significantly stronger than in prostate hyperplasia (t = 4.55, P < 0.05)." (PMID 18983683, 2008). "We present data that demonstrate that CD164 mRNA and protein is expressed by prostate cancer cell lines which are responsive to CXCL12 stimulation." (PMID 16859559, 2006). "We demonstrated previously that activation of CXCR4 by CXCL12 enhanced the adhesion of prostate cancer cells to bone marrow endothelial cells." (PMID 16859559, 2006). "While screening prostate cancers for CXCL12-responsive adhesion molecules, we identified CD164 (MGC-24) as a potential regulator of homing." (PMID 16859559, 2006). "Previously, we determined that the CXCL12/CXCR4 chemokine axis is activated in prostate cancers that metastasize to bone." (PMID 16859559, 2006). "CXCL12 enhanced the binding of prostate cancer cells to bone marrow endothelial cells, and CXCL12 up regulated the expression of CD164 mRNA and protein." (PMID 16859559, 2006). "One possibility is that the binding of CXCL12 to CXCR4 activates adhesion molecules that mediate the binding of prostate cancer cells to the bone marrow endothelium." (PMID 16859559, 2006). "Using prostate cancer cell lines, it was demonstrated that CXCL12 induced both the expression of CD164 mRNA and protein." (PMID 16859559, 2006). "We reported previously that CXCR4 expression is correlated with tumor grade, and that CXCL12 signaling through CXCR4 triggers the adhesion of prostate cancer cells to bone marrow endothelial cells." (PMID 16859559, 2006). "We noted previously that in vitro proliferation and intratibial growth of prostate cancers depends on CXCL12." (PMID 16859559, 2006). "To identify those molecules that are responsible for the CXCL12-induced changes in adhesion and invasion, we examined the patterns of prostate cancer gene expression in human tissues." (PMID 16859559, 2006).